CD24 (CD24 molecule)
Diseases named in the same sentence as CD24 in open-access papers (continued):
Sharing a sentence is not in itself a finding about the gene and the disease.
esophageal squamous cell carcinoma (4 papers, 2017 to 2024). Esophageal squamous cell carcinoma (ESCC) is a type of esophageal carcinoma (EC) that can affect any part of the esophagus, but is usually located in the upper or middle third. "Additionally, in esophageal squamous cell carcinoma, CD24 expression is also demonstrated to be linked to tumor lymph node metastasis, tumor grade, and survival time." (PMID 38881902, 2024).
graft versus host disease (4 papers, 2019 to 2023). An immune system disorder that occurs after allogeneic hematopoietic stem cell transplant and is a reaction of donor immune cells against host tissues. "Moreover, the Siglec-G/CD24 axis controls the severity of graft versus host disease (GVHD), and enhancing this interaction may mitigate GVHD." (PMID 32889432, 2020).
HIV-1 infection (4 papers, 2008 to 2025). The type species of lentivirus and the etiologic agent of acquired immunodeficiency syndrome (AIDS). "In this study, we assessed the therapeutic effect of CD24-Fc, a fusion protein with anti-inflammatory properties that interacts with danger-associated molecular patterns (DAMPs) and siglec-10, in chronic HIV-1 infection model using humanized mice undergoing suppressive cART." (PMID 39763958, 2024). "To assess the contribution of viral accessory proteins to the transcriptome changes observed upon HIV-1 infection we infected MDMs with a recombinant HIV-1Bal clone encoding murine CD24 (mCD24), herein referred to as WT or with accessory gene mutant HIV-1 viruses (dataset #2)." (PMID 35215107, 2022). "We tested the therapeutic effect of the anti-inflammatory fusion protein CD24-Fc in humanized mice with HIV-1 infection and suppressive cART in vivo and in PMBC from PWH with cART in vitro." (PMID 40779581, 2025). "We tested the therapeutic effect of the anti-inflammatory fusion protein CD24-Fc in humanized mice with HIV-1 infection and suppressive cART in vivo and in PMBCs from PWH with cART in vitro." (PMID 40779581, 2025). "We report that CD24-Fc treatment significantly reduced inflammation and immune hyperactivation in humanized mice with HIV-1 infection and cART." (PMID 40779581, 2025). "In this study, we evaluate the therapeutic potential of CD24-Fc in a chronic HIV-1 infection model using suppressive cART in humanized mice." (PMID 39763958, 2024). "We investigated the effects of CD24-Fc on HIV-1 reservoir, persistent inflammation and immune pathogenesis during cART in humanized mice engrafted with human immune cells that support HIV-1 infection and respond to cART with relevant inflammatory pathogenesis." (PMID 40779581, 2025). "For HIV-1 infection, CEM-SS were infected with NL4-3.HSA.R+E- (Vpr+, Env-), a VSV-G pseudotyped HIV strain with the murine heat stable antigen CD24 (HSA) gene inserted into the nef region to facilitate surface HSA staining of HIV-1-positive cells." (PMID 18439272, 2008).
influenza (4 papers, 2015 to 2025). An acute viral infection of the respiratory tract, occurring in isolated cases, in epidemics, or in pandemics; it is caused by serologically different strains of viruses (influenzaviruses) designated A, B, and C, has a 3-day incubation period, and usually lasts for 3 to 10 days. "Traditionally utilized for influenza treatment, OP's ability to target the CD24‐Siglec‐G/10 axis offers a strategic avenue to mitigate secondary brain injury after CA, bridging the gap between virology and neurocritical care." (PMID 40836885, 2025). "The effect of Clostridia against influenza and pneumonia was induced by up-regulating the IgD- CD24- B cell absolute count." (PMID 39062949, 2024). "The Eubacterium ruminantium group promoted influenza infection by increasing the number of CD25 on IgD+ CD24- B cells with a mediated effect of 4.07%." (PMID 39062949, 2024). "In the lung during influenza infection, CD103+ DCs induce effector CD8+ T cells via CD24, while CD11b+ DCs have reduced levels of CD24 and induce memory CD8+ T cells." (PMID 26124756, 2015).
kidney (4 papers, 2016 to 2024). "Similarly, in B cells, the presence of CD24 on IgD+ CD38- unsw mem cells (OR = 1.2797, 95% CI = 1.0090 to 1.6231, p = 0.0419) and IgD on IgD+ CD38- cells (OR = 1.6871, 95% CI = 1.2058 to 2.3605, p = 0.0022) has also been shown to be associated with an increased risk of prostatitis." (PMID 39323879, 2024). "This study provides, for the first time to the best of our knowledge, strong evidence that during AKI, CD24, which is not normally expressed in the mature kidney, is upregulated in the distal tubular epithelial cells, and its attenuation ameliorates kidney damage." (PMID 37511747, 2023).
mantle cell lymphoma (4 papers, 2022 to 2024). Mantle cell lymphoma is a rare form of malignant non-Hodgkin lymphoma affecting B lymphocytes in the lymph nodes in a region called the ``mantle zone''. "The CD24/Siglec-10 axis is another possible immunotherapeutic target for mantle cell lymphoma (MCL)." (PMID 38279998, 2024). "In mantle cell lymphoma (MCL) and follicular lymphoma patients, high mRNA expression of CD24 correlated with poor overall survival, whereas CD47 expression did not." (PMID 35625912, 2022).
prostate adenocarcinoma (4 papers, 2018 to 2025). "In light of these considerations, this study aims to bridge existing gaps in knowledge by thoroughly examining the expression of the CD24 marker and its nuanced relationship with benign prostatic hyperplasia and Gleason grade in prostate adenocarcinoma." (PMID 39687458, 2024). "In prostate adenocarcinoma patients, CD24 expression percentage and staining intensity were significantly higher than in BPH patients." (PMID 39687458, 2024). "The percentage and intensity of CD24 staining in prostate adenocarcinoma patients was significantly higher than in BPH patients (P<0.05)." (PMID 39687458, 2024). "The aim of this investigation was to assess the CD24 expression and its association with BPH and Gleason grade in prostate adenocarcinoma." (PMID 39687458, 2024). "Immunohistochemical staining was used to evaluate CD24 expression, and Gleason grade was determined in the case of prostate adenocarcinoma." (PMID 39687458, 2024). "This lacuna underscores the need for a comprehensive investigation into the expression of the CD24 marker and its correlation with benign prostatic hyperplasia and Gleason grade in prostate adenocarcinoma." (PMID 39687458, 2024). "CD24 expression can be considered as a factor in differentiating cases of prostate adenocarcinoma from benign prostatic hyperplasia." (PMID 39687458, 2024). "The mean percentage of CD24 expression (Percentage of stained cells) in patients with prostate adenocarcinoma (36.69±27.21%) was significantly higher than that of BPH patients (11.61±10.68%) (P<0.001)." (PMID 39687458, 2024). "CD24 expression is a factor that can help distinguish between cases of prostate adenocarcinoma and BPH." (PMID 39687458, 2024). "Also, the CD24 staining intensity in the prostate adenocarcinoma group (1.87±1.02) was significantly higher than that of BPH patients (0.90±0.78) (P<0.001)." (PMID 39687458, 2024). "IHC analysis of prostate adenocarcinoma samples showed frequent coexpression of CD24 (49%) and RCC2 (82%) with a positive correlation between coexpression of CD24 (49%) and RCC2 (82%)." (PMID 41090358, 2025). "This study aims to investigate the relationship between immunohistochemical expression of CD24 and its relationship with benign prostatic hyperplasia (BPH) and Gleason grade in prostate adenocarcinoma." (PMID 39687458, 2024). "CD24 expression in more than 50% of cells was observed in 28.2% of patients with prostate adenocarcinoma, whereas none of the patients with BPH showed an expression percentage higher than 50%." (PMID 39687458, 2024).
salivary gland tumors (4 papers, 2013 to 2023). "A diagnostic CSCs biomarker in salivary gland tumors was recently assessed using gold nanoparticles that were designed and integrated with CD24 primer to create a CD24-AuNP." (PMID 37508788, 2023). "The immunophenotype CD44+/CD24- was the most prevalent, appearing in 52,2% of salivary glands tumors." (PMID 23419168, 2013).
sarcoma (4 papers, 2014 to 2024). A usually aggressive malignant neoplasm of the soft tissue or bone. "We exposed human sarcoma cell lines to sorafenib, regorafenib, and pazopanib and assessed cell viability and expression of CSC markers (ALDH, CD24, CD44, and CD133)." (PMID 25301268, 2014). "Specifically, we identified two main populations of IFN–CSCs in MCA205 sarcoma cells: the CD133+CD24+CD44+low (CD44L, ~7 times higher compared with the untreated condition, (CTR)) and the CD133+CD24+CD44+high (CD44H, ~9 times higher compared with the CTR) CSC subsets." (PMID 36002648, 2022). "In contrast, we observed CD24, CD44, and CD133 to be variably expressed in our sarcoma cell lines, and we found that these markers did not reliably correlate with the CSC phenotype." (PMID 25301268, 2014). "However, a negative correlation was observed between CD24 expression levels and the abundance of TILs in COAD, BLCA, and sarcoma (SARC)." (PMID 39791710, 2024).
urothelial carcinoma (4 papers, 2014 to 2025). A malignant neoplasm derived from the transitional epithelium of the urinary tract (urinary bladder, ureter, urethra, or renal pelvis). "The ALB9 mAb blocked human urothelial carcinoma cells that overexpressed CD24 from spreading to the lungs, but lung colonization soon returned after the treatment was terminated." (PMID 37846296, 2023). "In human urothelial carcinoma, CD24 expression is controlled by androgen receptors." (PMID 40486886, 2025). "In addition, expression of CD24 on urothelial carcinoma is androgen regulated." (PMID 35628262, 2022).
acute lymphoblastic leukemia (3 papers, 2022 to 2025). Leukemia with an acute onset, characterized by the presence of lymphoblasts in the bone marrow and the peripheral blood. "As an alternative to targeting CD24 in malignancies, ScFvs have FDA approval for clinical use, including blinatumomab for acute lymphoblastic leukemia." (PMID 37846296, 2023). "Flow cytometry confirmed precursor B-cell acute lymphoblastic leukemia (B-ALL), with the blasts expressing CD123, CD73/86, CD9, CD34, TdT, HLA-DR, CD58, CD38, cCD22, sCD22, cCD79a, and CD19, along with partial expression of CD24 and aberrant CD33." (PMID 40718322, 2025). "Given that AML has a low expression of CD24, and acute lymphoblastic leukemia (ALL) and DLBCL have a moderate/high expression of CD24, it stands to reason that ALL and DLBCL may effectively respond to anti-CD24 treatment." (PMID 35978372, 2022).
AIDS (3 papers, 2019 to 2025). A syndrome resulting from the acquired deficiency of cellular immunity caused by the human immunodeficiency virus (HIV). "CD24-Fc conferred protection against weight loss, wasting syndrome, intractable diarrhea, and decreased AIDS morbidity and mortality in pathogenic SIV infection." (PMID 39763958, 2024). "CD24-Fc conferred protection against SIV-induced wasting syndrome, intractable diarrhea, and decreased AIDS morbidity and mortality in NHP with pathogenic SIV infection." (PMID 40779581, 2025). "Preclinical research on CD24-Fc in SIV-infected primates suggests it can reduce inflammation and slow AIDS progression, showing promise for managing chronic immune activation in HIV and SIV infections." (PMID 39763958, 2024). "Here we show that Breg cells (CD19+CD24++CD38++), as well as B cells expressing PD-L1 (CD19+PD-L1+ cells), are elevated prior to AIDS-NHL diagnosis." (PMID 31253857, 2019). "In SIV-infected non-human primates without cART, CD24-Fc is able to reduce inflammation, alleviate chronic immune activation and slow down AIDS progression." (PMID 40779581, 2025). "Here we show that numbers of both Breg cells (CD19+CD24++CD38++ cells) and CD19+PD-L1+ cells were elevated in the peripheral circulation of HIV+ subjects prior to AIDS-NHL diagnosis, when compared to the levels seen in HIV+ controls who did not develop AIDS-NHL." (PMID 31253857, 2019). "It was seen that the number of CD19+CD24++CD38++and CD19+PD-L1+cells was significantly elevated in cases 1–4 years prior to AIDS-NHL diagnosis, compared to controls, raising the possibility that these cells may play a role in the etiology of AIDS-NHL." (PMID 31253857, 2019). "We observed that the majority of the PD-L1+ B cells had a phenotype consistent with that of Breg cells (CD19+CD24++CD38++), indicating that these PD-L1+ B cells are a subpopulation of the so-called Breg cell population, at least in these HIV+ subjects who went on to develop AIDS-NHL." (PMID 31253857, 2019).
Allergy (3 papers, 2021 to 2023). An allergy is an immune response or reaction to substances that are usually not harmful. "Maternal and cord plasma at delivery could predict the number of CD24+CD38low memory B-cells (p = 0.033, n = 26 and p = 0.009, n = 22), but future allergy status could not be distinguished from any of the three measured metabolomes." (PMID 34135462, 2021).
Alzheimer disease (3 papers, 2012 to 2025). A progressive, neurodegenerative disease characterized by loss of function and death of nerve cells in several areas of the brain leading to loss of cognitive function such as memory and language. "Our analysis identifies specific subgroups of immune cells including CD38 on IgD- CD38br, IgD on IgD + CD24+, IgD on IgD + CD38br,IgD on IgD+, as potential risk factors for Alzheimer’s disease through Mendelian randomization analysis." (PMID 38500057, 2024). "Finally, the gene ranked 5th overall, BCL6, is (together with CD24) the only immunity-related gene with significantly higher expression in severe Alzheimer’s disease that was singled out by principal component analysis (PCA)." (PMID 23066814, 2012).
Arthritis (3 papers, 2013 to 2024). Inflammation of a joint. "Additionally, a former study demonstrated that intestinal microbiota-derived butyrate activated AhR, a functional transcriptional marker of CD19+CD21+CD24+ Breg cells, in a Breg cell-dependent manner, which inhibited arthritis and reduced arthritis severity." (PMID 39478858, 2024). "The mechanisms by which 20S(OH)D3 downregulates arthritis severity in the CIA model is likely related to reduction in CD4+ T cells, CD19+ B cells, anti-CII antibodies, and maintenance of CD4+CD24+FoxP3+Tregs." (PMID 34276665, 2021).
bladder tumor (3 papers, 2013 to 2023). "Intensive yellow staining provided evidence for a prominent co-expression of tumor marker GATA-3 and the AE1/AE3 reactive cytokeratins on UCO#33 by immunofluorescence as well as co-expression of bladder tumor-associated antigens CD24 and of CD44." (PMID 37626918, 2023). "The results demonstrated that CD24 expression is significantly associated with bladder tumor recurrence." (PMID 23946784, 2013). "Positive CD24 expression was significantly associated with intra-bladder tumor recurrence following surgery." (PMID 23946784, 2013). "Positive CD24 expression was significantly associated with intra-bladder tumor recurrence following surgery and increased staining intensity was also correlated with recurrence." (PMID 23946784, 2013). "CD24 expression has also been associated with bladder tumor recurrence." (PMID 28611669, 2017). "There was a significant association between CD24 expression and the cancer grade and the recurrence of the bladder tumors [low-grade (G1, 8 out of 29, 27.6%) and high-grade (G2–G3, 71 out of 96, 74.0%); recurrence-negative (22 out of 58, 37.9%) and recurrence-positive (57 out of 67, 85.1%)]." (PMID 23946784, 2013). "In the present study, the CD24 expression in cancer tissues obtained during transurethral surgery and the subsequent intra-bladder tumor recurrence following surgery were assessed." (PMID 23946784, 2013). "CD24 expression was observed more frequently in high-grade bladder tumors (G2–G3) than low-grade tumors (G1)." (PMID 23946784, 2013). "Based on this background, the present study focused on the expression of CD24, a possible cancer cell dissemination-related factor, in human superficial bladder cancer and investigated its correlation with intra-bladder tumor recurrence following transurethral surgical treatment." (PMID 23946784, 2013).
Burkitt lymphoma (3 papers, 2012 to 2022). A rare form of malignant mature B-cell non-Hodgkin lymphoma. "Three research groups reported that CD24 interacted with Lyn directly or indirectly in monocytic ESb-MP cells, in the erythroleukaemia cell line K562 and in the Burkitt’s lymphoma (BL)-derived cell line P32/SH." (PMID 22731636, 2012).
chronic lymphocytic leukaemia (3 papers, 2023 to 2024). "Immunophenotype of MCL cells is also characterized by the co-expression of CD5 and pan B-cell antigens (CD19, CD20, CD22, and CD24), which are also detectable in CLL/small lymphocytic lymphoma." (PMID 36624655, 2023).
chronic pancreatitis (3 papers, 2017). A chronic inflammatory process causing damage and fibrosis of the pancreatic parenchyma. "ANXA10 and CD24 positive rates as well as the co-expression rate in normal pancreas, cancer adjacent normal pancreas tissues, chronic pancreatitis, PanINs, IPMNs, and PDACs, respectively." (PMID 28369074, 2017). "CD24 expression in chronic pancreatitis was heterogeneous, and about 30–50% cells were CD24-positive in these chronic pancreatitis specimens." (PMID 28369074, 2017). "2D plots of ANXA10 and CD24 staining scores in various disease groups, including normal pancreas, chronic pancreatitis (CP), low- and high-grade IPMNs, low- and high-grade PanINs, early- and late-stage PDACs, were generated using SPSS16.0." (PMID 28369074, 2017). "The immunofluorescence staining was performed to evaluate ANXA10 and CD24 expression in chronic pancreatitis (CP, n = 5)." (PMID 28369074, 2017). "Surgical specimens from 23 patients with PDAC and 15 patients with chronic pancreatitis after pancreatic resection were stained with CD24, CD44, and CD133 antibodies." (PMID 28659655, 2017). "However, positive CD24 expression was observed in all 5 cases of chronic pancreatitis specimens investigated in this study." (PMID 28369074, 2017). "CD24 as a glycosylphosphatidylinositol-anchored membrane protein also plays a role in B-cell development, which may help explain the immunoreactivity of CD24 in chronic pancreatitis." (PMID 28369074, 2017). "Chronic pancreatitis tissues were found in the upper left panel of the plot, with low ANXA10 scores but high CD24 scores." (PMID 28369074, 2017). "So far, there is very little data regarding the comparison of the expression of CD24, CD44, and CD133 in PDAC and chronic pancreatitis (CP)." (PMID 28659655, 2017).
colon adenocarcinoma (3 papers, 2015 to 2024). "Pancreatic and colon adenocarcinoma cells treated in vitro with shRNA reportedly downregulated CD24 expression and had impaired cell growth and motility." (PMID 26394139, 2015).
cyst (3 papers, 2017 to 2024). A sac-like closed membranous structure that may be empty or contain fluid or amorphous material. "Rapamycin decreases the proliferation of CD133+ and CD24+ cells and cyst formation in vitro through inhibition of the mechanistic target of rapamycin (mTOR) in PKD." (PMID 28535817, 2017). "In three dimensional (3D) culture, CD24+ cells formed small cysts slightly more frequently that CD24− ones, though the difference in the capability forming the cyst structure was not substantially different between these two populations." (PMID 28051157, 2017).
follicular lymphoma (3 papers, 2021 to 2023). Follicular lymphoma is a form of non-Hodgkin lymphoma characterized by a proliferation of B cells whose nodular structure of follicular architecture is preserved. "CLL and MCL, as well as Follicular Lymphoma (FL) and Marginal‐zone Lymphoma (MZL), showed higher expression of CD24 in comparison to B cells from healthy subjects." (PMID 37654003, 2023).